HIF1A (hypoxia inducible factor 1 subunit alpha)
Diseases named in the same sentence as HIF1A in open-access papers (continued):
Sharing a sentence is not in itself a finding about the gene and the disease.
squamous cell carcinoma (34 papers, 2009 to 2026). A carcinoma arising from squamous epithelial cells. "In stratified analysis, we found that the plasma level of HIF-1α of patients with squamous cell carcinomas was associated with regional lymph node status." (PMID 26853843, 2016). "In stratified analysis, the plasma level of HIF-1α in patients with squamous cell carcinoma is associated with regional lymph node status." (PMID 26853843, 2016). "In a head and neck (H&N) series, high expression of HIF1α in 79 surgically treated patients with squamous cell carcinoma was significantly associated with improved disease-free and overall survival in multivariate analysis." (PMID 22546016, 2012). "We analyzed subgroups according to the combinations of SLC2A1, VEGFA, APEX1, and HIF1A polymorphisms in patients with squamous cell carcinomas." (PMID 20540786, 2010). "Furthermore, high expression of HIF1α in patients treated with postoperative radiotherapy was associated with survival, therefore being a novel prognostic marker in squamous cell carcinoma of the mouth." (PMID 23028863, 2012). "Moreover, in patients treated with postoperative radiotherapy, high HIF1α expression was associated with survival, therefore being a novel prognostic marker in squamous cell carcinoma of the oral cavity." (PMID 23028863, 2012). "pTNM stage (P = 0.002) and the plasma level of HIF-1α (P = 0.028) were independent prognostic factors of patients with squamous cell carcinomas." (PMID 26853843, 2016). "There was a significant relationship between 5-year postoperative survival rate of patients with squamous cell carcinomas and the plasma level of HIF-1α." (PMID 26853843, 2016). "HIF-1α was the only factor to demonstrate a higher expression level in adenocarcinomas compared with the squamous cell carcinomas." (PMID 26622782, 2015). "Taken together, these observations suggest that high expression of HIF-1α or CAIX cannot be clinically useful biomarkers of poor outcome in squamous cell carcinoma of the uterine cervix." (PMID 26502718, 2015). "Lack of CAIX and Glut-I expression along with high HIF-1α expression in squamous cell carcinoma indicates alternative mechanism for HIF-1α upregulation." (PMID 24165149, 2013). "The results of the Western immunoblot test performed on tissue material revealed significant differences in the expression of selected proteins involved in apoptosis-related proline metabolism (PRODH/POX, PPARγ, HIF-1α) between squamous cell carcinoma and normal mucosa." (PMID 31935820, 2020). "In the present study, we have evaluated a large series of primary vulvar squamous cell carcinomas for primary tumor vascularity and expression of HIF-1α and VEGF and elucidated their relationships with various clinicopathological parameters and clinical outcome." (PMID 24165149, 2013). "Furthermore, we have shown that the patients in good prognosis group had >50% HIF-1α positive tumor cells as reported for its strong expression in squamous cell carcinoma of oral cavity." (PMID 24165149, 2013). "Likewise, HIF1α expression was assessed in 85 patients with early stage T1−2 H&N squamous cell carcinoma treated with surgery alone by IHC on tissue micro arrays." (PMID 22546016, 2012). "Additionally, Fillies and cols, described a better prognosis for patients with high HIF1α expression in squamous cell carcinomas of the tongue basis treated with radiotherapy." (PMID 23028863, 2012). "In this study, we investigated HIF1α expression by immunohistochemistry in tissue microarrays and its relationship with clinical findings, histopathological results and survival of 66 patients with squamous cell carcinoma of the lower mouth." (PMID 23028863, 2012). "Through separate mechanistic amelioration of HIF-1α and HIF-1β and their regulators—miRNA-21 and miRNA-210 - the fractions SD2 and SD3 revealed a possible anti-hypoxia impact in Tongue Squamous Cell Carcinoma (CAL27) cells." (PMID 35399691, 2022).
squamous cell carcinoma (continued). "Results indicated that c-Myc, c-Jun, Bcl-2, hypoxia inducible factor-1α (HIF-1α), vascular endothelial growth factor (VEGF), matrix metalloproteinase-9 (MMP-9), ERK 1/2 and pERK1/2 were overexpressed in a cellular model of squamous cell carcinoma, Cal-27." (PMID 35890188, 2022). "Tumor vascularity using CD34 stained slides measured by Chalkley counting method as well as hypoxia-inducible factor (HIF)-1α and vascular endothelial growth factor (VEGF) immunoexpression was examined in 158 vulvar squamous cell carcinomas." (PMID 24165149, 2013). "We confirmed that erlotinib inhibited HIF-1α and VEGF both in vitro and in vivo in SQ20B squamous cell carcinoma cells." (PMID 19657384, 2009). "HIF1A and MMP3: Previous studies have highlighted their roles in promoting invasion and metastasis in other squamous cell carcinomas or skin tumors, this study for the first time links both genes to the PI3K/AKT/mTOR signalling pathway and validates their expression changes via qPCR." (PMID 41438693, 2026). "Their combined radiogenomic model for predicting histotype (squamous cell carcinoma or adenoma) contained the same two genes (HIF1A and TP63) as their best model based on genes alone and no radiomic features." (PMID 35742947, 2022). "Our result showed that HIF1α was highly expressed in squamous cell carcinoma of cervix exposed to hypoxia, which, not coincidentally, complied with a previous study that HIF1α expression was increased in CC cells under hypoxia." (PMID 35287356, 2022). "In this study, the 5-year survival rate of patients with squamous cell carcinomas which their plasma level of HIF-1α lower than median was 78.6%, and much greater than the 5-year survival rate of those which the plasma level of HIF-1α higher than median (50.0%) (P = 0.034)." (PMID 26853843, 2016). "Although in the analysis of prognostic factors, the plasma level of HIF-1α was not a prognostic factor of patients with NSCLC, and was associated with the 5-year survival rate of patients with squamous cell carcinomas." (PMID 26853843, 2016). "The results indicated that the 5-year survival rate of patients with squamous cell carcinomas is negatively correlated with the plasma level of HIF-1α and the 5-year survival rate of patients with low level of HIF-1α is higher than those with high level of HIF-1α." (PMID 26853843, 2016). "In addition, when HIF-1α overexpression was evaluated by univariate analysis for a relationship to outcome according to different histological subtypes, there was a trend towards worse DSS in squamous cell carcinomas (median survival time; 52 vs 62 months) (P=0.07)." (PMID 20461082, 2010).
cholangiocarcinoma (32 papers, 2013 to 2025). A carcinoma that arises from the intrahepatic biliary tree (intrahepatic cholangiocarcinoma) or from the junction, or adjacent to the junction, of the right and left hepatic ducts (hilar cholangiocarcinoma). "Under hypoxic conditions, SKA3 recruits PARP1 to bind with HIF-1α, thereby enhancing USP7-mediated deubiquitination of HIF-1α, promoting the proliferation and fatty acid synthesis of cholangiocarcinoma cells." (PMID 39944823, 2025). "Recent research has identified that WDR5 promotes epithelial–mesenchymal transition (EMT) and metastasis in cholangiocarcinoma by enhancing HIF-1α accumulation through MYC-dependent pathways." (PMID 39757165, 2025). "The activation of PAK1 in a human cholangiocarcinoma cell impedes the degradation of hypoxia-inducible factor 1 alpha (HIF-1α) protein." (PMID 38067120, 2023). "HIF-1α levels are significantly elevated in cholangiocarcinoma cell lines compared to normal biliary cells and HIF-1α is important for cholangiocarcinoma cell line proliferation, migration, and invasion." (PMID 35360246, 2022). "Our in silico analysis revealed that a total of six TFs (SP1, CREB1, MAX, FHL2, RFX1 and HIF1A) were upregulated in cholangiocarcinoma tissues." (PMID 34199886, 2021). "HIF-1α/NRP-1 in fibrosarcoma and HIF-1α in cholangiocarcinoma can promote vasculogenic mimicry under hypoxic conditions." (PMID 32993787, 2020). "It was found that 66.0% (n=29/44) of the cholangiocarcinoma specimens were strongly positive for HIF-1α expression." (PMID 26018028, 2015). "In several studies, WDR5 promoted HIF-1α activity and HIF-1α was reported to be an important effector in WDR5-induced cholangiocarcinoma metastasis under 95% air and 5% CO2 instead of hypoxia treatment." (PMID 39757165, 2025). "HIF-1α and FOSL1 played crucial roles in driving the proliferation, invasion, and migration of cholangiocarcinoma cells within the tumor microenvironment, orchestrated by CAFs." (PMID 41048570, 2025). "In cholangiocarcinoma cells, upon photodynamic therapy, increased PAK1 regulates the stability of HIF-1α by inhibiting HIF-1α ubiquitination–mediated degradation and promotes angiogenesis." (PMID 36830998, 2023). "SIRT3, downregulated in cholangiocarcinoma (CCA) patients, can prevent tumor progression by inhibiting the HIF1α/PDK1/PDHA1 pathway." (PMID 35136826, 2022). "We found that in both the pancreatic and cholangiocarcinoma models, GEM implantation reduced tumor growth by affecting vascularization by reducing VEGF, VEGFR2, CD31, and HIF-1α protein levels." (PMID 32111094, 2020). "We determined the gene expressions of FLT1, FLT4, HPSE, Hif1a, HB-EGF, PDGFA, PDGF-RA and EGFR in FFPE samples of patients with cholangiocarcinoma." (PMID 23704979, 2013). "Although previous studies have reported that SKA3 interacted with PARP1/HIF-1α to promote cholangiocarcinoma proliferation, our findings did not reveal a direct interaction between SKA3 and HIF-1α in LUAD." (PMID 41298345, 2025). "Targeting the USP21/HSP90/HIF1α and USP21/ENO1 signaling axes may provide a rational basis for precision therapies and improved prognostication in cholangiocarcinoma." (PMID 41301681, 2025). "Moreover, metformin also sensitizes cholangiocarcinoma cells to chemotherapeutic agents such as sorafenib, 5-fluorouracil, and arsenic trioxide by regulating the AMPK/mTOR/HIF-1α/MRP1 pathway and ERK." (PMID 36837499, 2023). "WDR5 could interact with the MBIIIb motif of c-Myc and facilitate Myc-induced HIF1-α transcription, therefore promoting the EMT, invasion and metastasis of cholangiocarcinoma (CCA)." (PMID 34658888, 2021). "Moreover, expressions of six TF genes (SP1, CREB1, MAX, FHL2, RFX1, and HIF1A) was positively correlated with the expression of ITGA6 and ITGB1 in cholangiocarcinoma tissues." (PMID 34199886, 2021). "For example, HIF1A is the only pathway activated in over 90% of the non-T cell-inflamed tumors in cholangiocarcinoma, perhaps emphasizing it as a therapeutic target." (PMID 33106165, 2020).
cholangiocarcinoma (continued). "In these cancerous tissues, HIF-1α-specific signals were localized mainly in the cytoplasm of cholangiocarcinoma cells but not in normal biliary epithelial cells." (PMID 26018028, 2015). "In addition, immunohistochemical analysis indicated that HIF-1α is preferentially expressed in cholangiocarcinoma but not in the adjacent normal bile duct tissues obtained through biopsy from cholangiocarcinoma patients." (PMID 26018028, 2015). "However, this association was not significant in the examined study group of patients with cholangiocarcinoma which is in concordance with discoveries from other groups examining Hif1a in CCC who were also not able to show a correlation of Hif1a expression to survival." (PMID 23704979, 2013). "Furthermore, patients with cholangiocarcinoma had poor prognoses and overall survival regardless of whether USP21 was highly expressed simultaneously with HSP90 or HIF1A." (PMID 38385089, 2024).
autoimmune disease (31 papers, 2018 to 2026). A disorder resulting from loss of function or tissue destruction of an organ or multiple organs, arising from humoral or cellular immune responses of the individual to their own tissue constituents. "Although the immunostimulatory effects of HIF-1α in certain autoimmune diseases are well documented, its role and underlying mechanisms remain controversial." (PMID 41956208, 2026). "HIF-1α mutations have not only been shown for T1D but also for many other autoimmune diseases and thus again link seasonal changes with genetic predisposition for autoimmune disease." (PMID 32650582, 2020). "Taken together, this study demonstrates the key function of the hypoxia-associated transcription factor HIF-1α in driving IL-10 expression in CD1dhiCD5+ B cells, and in controlling their protective activity in autoimmune disease." (PMID 29343683, 2018). "Taken together, these findings show that the loss of HIF-1α in B cells causes impaired IL-10 production and aggravating autoimmune diseases." (PMID 29343683, 2018). "HIF-1α and other hypoxia-induced mechanisms may be the missing link to understand the increased risk of tumorigenesis in those patients suffering from autoimmune diseases." (PMID 40963621, 2025). "A previous study of a case of VHL disease and another autoimmune disease, myasthenia gravis, investigated the role of the HIF-1α pathway and hypoxia in inflammatory response, underlining the need for further insight into the clinical, genetic, and molecular overlap of neoplasia and autoimmunity." (PMID 38619811, 2024). "Gene polymorphism studies may provide basic data for the treatment and prevention of autoimmune disorders by revealing the risk of HIF-1α in autoimmune diseases, disease phenotype, and responsiveness to drug treatment." (PMID 36761171, 2022). "Wild-type CD1dhiCD5+ B cells, but not Hif1a-deficient CD1dhiCD5+ B cells, protect recipient mice from autoimmune disease, while the protective function of Hif1a-deficient CD1dhiCD5+ B cells is restored when their defective IL-10 expression is genetically corrected." (PMID 29343683, 2018). "We next used a similar genetic approach to test whether the suppressive defect of Hif1a-deficient CD1dhiCD5+ B cells in autoimmune disease could similarly be rescued by genetically ecotopic-expressing IL-10." (PMID 29343683, 2018). "We will discuss mechanisms through which disruptions in innate immunity contribute to autoimmune disease pathogenesis and the divergent immunomodulatory effects that HIF-1α exerts in various autoimmune disorders." (PMID 41956208, 2026). "Meanwhile, we will also evaluate the value of compounds in HIF-1α-related disease such as ischemic cardiovascular disease, chronic inflammation and autoimmune diseases to further enhance the application value of this study." (PMID 40421268, 2025). "Both tumor and autoimmune diseases can be modulated by the hypoxia inducible factor alpha (HIF-1α) sharing similar molecular mechanisms." (PMID 40963621, 2025). "Taken together, these data show that DOCK8 can regulate the levels of glycolysis and oxidative phosphorylation by stabilizing the mTOR/HIF‐1α signaling pathway, thereby inhibiting the abnormal differentiation of Th17 cell and autoimmune disease development." (PMID 39329018, 2024). "The selective dependence of Th17 differentiation in HIF-1α-mediated metabolic reprogramming provides a new target for the treatment of inflammatory and autoimmune diseases directed by Th17." (PMID 36834484, 2023). "In this review, we narrate the signaling pathway of HIF-1α and the possible immunopathological roles of HIF-1α in autoimmune diseases." (PMID 36761171, 2022). "If specific regulatory role between IL-38 and SIRT1/HIF-1α signaling pathway in autoimmune diseases is clearly understood, it will provide new methods for treatments." (PMID 34539413, 2021).
autoimmune disease (continued). "In fact, targeting HIF-1α in animal models of autoimmune diseases and cancer has yielded encouraging results and new pharmacological approaches." (PMID 33808042, 2021). "TH17 cells are induced by IL-6 and TGF-β in a HIF-1α-dependent manner, they play an important role in autoimmune diseases." (PMID 29762526, 2018). "Collectively, our results demonstrate that HIF-1α expression in B cells has a crucial protective function in autoimmune diseases." (PMID 29343683, 2018). "Next, we delineated the physiological relevance of the immunoregulation of HIF-1α on IL-10-producing B cells and the protective role of HIF-1α-deficient B cells in autoimmune disease." (PMID 31225473, 2018). "In consequence, HIF-1α activation in B cells regulates autoimmune diseases such as experimental autoimmune encephalomyelitis (EAE) and arthritis." (PMID 29762526, 2018). "We generated B cell-specific Hif1a or Hif2a mutant mice to test the influence of HIFs on B cell cytokine production and on the course of autoimmune disease." (PMID 29343683, 2018). "Our findings indicate that HIF-1α is a key element for IL-10-producing B cell proliferation and IL-10 signaling, thereby influencing the course of T cell mediated autoimmune diseases such as EAE and arthritis." (PMID 31225473, 2018). "Accordingly, we found that CD44hiCD138+ plasmablasts are also reduced in Hif1a-deficient mice after EAE induction, suggesting that loss of HIF-1α causes impaired CD1dhiCD5+ B cells and increases likelihood to develop autoimmune disease." (PMID 29343683, 2018). "We identified HIF-1α as a critical transcriptional factor involved in IL-10 production by B cells, thereby influencing the course of autoimmune diseases." (PMID 31225473, 2018). "Finally, we will examine the pharmacological potential of HIF-1α modulation to regulate innate immunity prior to the development of autoimmune diseases." (PMID 41956208, 2026). "Also, HIF-1α has a crucial effect on innate and adaptive immune responses and is related to inflammation and pathological activity of autoimmune diseases." (PMID 34539413, 2021). "These and other findings reported and reviewed here suggest that targeting HIF-1α could be a useful strategy for autoimmune diseases therapies." (PMID 33808042, 2021). "Because of its significant impact on inflammation and immune-mediated inflammatory diseases (IMIDs) including autoimmune diseases and cancer, HIF-1α could serve as a promising therapeutic target." (PMID 33808042, 2021). "Moreover, HIF-1α also invokes the differentiation of Th0 lymphocytes into Th17 cells, which are important for autoimmune disease development, including RA." (PMID 29598831, 2018). "HIF-1α expression controls CD1dhiCD5+ B cells expansion and may be considered as a potential target in autoimmune disease." (PMID 29343683, 2018). "In consequence, HIF-1α expression in B cells regulates autoimmune disease." (PMID 31225473, 2018). "Thus, the evidence suggests a common mechanism in tumor progression and autoimmune disease development involving the regulation of HIF-1α, which contributes to the differentiation of T cells into pro-inflammatory cells characteristic of many autoimmune diseases." (PMID 40963621, 2025). "Interestingly, hypoxia-inducible factor 1-alpha (Hif-1α), the main hypoxia-initiated transcription regulator, was shown to drive IL-10 expression in CD1dhiCD5+ B cells, hence exerting their protective roles in autoimmune diseases." (PMID 32566686, 2020). "Therefore, we hypothesized that HIF-1α in B cells represented a critical node for the modulation of autoimmune diseases." (PMID 29343683, 2018). "Targeting this axis, for instance through combined HIF-1α inhibitors and IDO1/AhR pathway agonists, holds promise as a novel metabolic intervention strategy for autoimmune diseases." (PMID 41869303, 2026).